CCL20 (C-C motif chemokine ligand 20)
Diseases named in the same sentence as CCL20 in open-access papers (continued):
Sharing a sentence is not in itself a finding about the gene and the disease.
cervical carcinoma (23 papers, 2012 to 2025). A carcinoma arising from either the exocervical squamous epithelium or the endocervical glandular epithelium. "In the multivariate Cox regression, N1 stage, high-risk score, and the genes TNF, ITGA5, CXCL1, and CCL20 were observed to be significantly associated with increased risk in cervical cancer patients." (PMID 40517358, 2025). "Thorough analysis demonstrated that cervical cancer-derived IL-6 drives C/EBPβ-mediated CCL20 induction in cancer-associated fibroblasts and CCL20/CCR6-dependent Th17 recruitment." (PMID 28895886, 2017). "Mechanisms underlying stromal CCL20 expression remained unclear until cervical cancer explant cultures revealed that cancer-associated fibroblasts produce enormous amounts of CCL20." (PMID 28895886, 2017). "In cervical cancer, CCL20 derived from stromal fibroblast promoted the progression of cervical cancer through CCL20-mediated recruitment of Th17." (PMID 39985603, 2025). "In cervical cancer, CCL20 modulates immune cell infiltration through its receptor CCR6, promoting tumor progression." (PMID 40517358, 2025). "In cervical cancer, CCL20 promoted an immunosuppressive tumor microenvironment by enhancing M2 macrophage infiltration while inhibiting CD8 + T cell infiltration." (PMID 39985603, 2025). "Epiregulin was positively correlated with most chemokines, such as CXCL1, CXCL2, CXCL3, CXCL5, CXCL6, CXCL8, and CCL20, in most types of cancer, including cervical cancer." (PMID 37020674, 2023). "Th17 cells can be recruited to the TIME via the CCR6-CCL20 pathway in cervical cancer due to upregulated CCL20 in tumor tissues and high expression of CCR6 on Th17 cells aggregated within tumor tissues." (PMID 33868269, 2021). "Another study has shown that IL6 derived from cervical cancer cells stimulates cervical fibroblasts and induces CCL20 secretion via the CCAAT/enhancer-binding protein β pathway." (PMID 32707869, 2020). "CCL20 is also predominantly expressed in the stroma of cervical cancer tissue and correlates with stromal infiltration of CD4+IL17+ cells and with advancing International Federation of Gynecology and Obstetrics (FIGO) stage." (PMID 32707869, 2020). "Stromal fibroblasts induce CCL20 through IL6/C/EBPβ to support the recruitment of Th17 cells during cervical cancer progression." (PMID 31395078, 2019). "The chemokines controlling lymphocyte trafficking to HPV skin are under investigation with one report suggesting that Th17 cells infiltrate human cervical cancer via CCR6/CCL20 interactions." (PMID 28523003, 2017). "In line with this, E6 and E7 silencing in the HPV16-positive cervical cancer cell line SiHa restored nuclear expression of NF-κB subunits and increased CCL20 expression." (PMID 22911498, 2012). "Interestingly, CCL20 is involved in the migration of Th17 cells into tumour tissue in cervical cancer and contributes to immunopathogenesis." (PMID 39712018, 2024). "Furthermore, cervical cancer cells instruct primary cervical fibroblasts to produce high levels of CCL20 and to attract CD4+IL17+CCR6+ cells." (PMID 32707869, 2020). "All in all, the regulation of CCL20 on the tumor immune microenvironment is currently controversial, our research might have shed light upon an indispensable role for M2 macrophages as well in cervical cancer." (PMID 37183243, 2023). "The transcription level of the CCL20 and CDKN2A genes becomes increased at the stage of neoplastic epithelial changes and stays so in cervical cancer." (PMID 38946889, 2024). "Vimentin was found to be upregulated by treatment of cervical cancer cells with TGF-β; IL-6; and with chemokine CCL20." (PMID 36766756, 2023). "N-cadherin was upregulated when cervical cancer cells were treated with TGF-β, TNF-α, and chemokine CCL20." (PMID 36766756, 2023). "A reduced expression of E-cadherin was reported as a result of TGF-β treatment of cervical cancer cells, TNF-α treatment, IL-6 treatment, and treatment with Chemokine (C–C motif) ligand 20 (CCL20)." (PMID 36766756, 2023).
cervical carcinoma (continued). "Second, the circulating Th17 from patients with cervical cancer highly expressed CCR6, and selectively migrate in response to CCL20 in vitro." (PMID 25768730, 2015). "This implies that AEG is an important component of the CCL20/CCR6-Erk1/2-Akt-EMT pathway and could be a novel targeted therapy for cervical cancer." (PMID 36766756, 2023). "Moreover, in cervical cancer, increasing CD45RA+/CD45RO+ and decreasing CCL20+/CCR6+ expression correlated with neoplasia severity." (PMID 35805132, 2022). "One study has shown that level of CCL20 in the cervical cancer tissues is significantly higher than that in non-tumor and normal control tissues and strongly positively associates with Th17 cells." (PMID 32707869, 2020). "Moreover, one study has shown that CCL20 chemoattracts Th17 in vitro, while Th17, highly expressing CCR6, is significantly accumulated in cervical cancer tissue." (PMID 32707869, 2020). "The study also indicated that microRNA-21 could change proliferation, migration and apoptosis possible by controlling CCL20 in human cervical cancer cells, but the mechanism was not made clear." (PMID 35895593, 2022).
colon carcinoma (19 papers, 2009 to 2024). "In accordance with these data, another study demonstrated that increased expression of the CCR6 ligand CCL20 in colon tumor tissue was associated with worse overall survival of CRC patients under neoadjuvant chemotherapy." (PMID 36428508, 2022). "CCL20 is produced by colon cancer cells and tumor-associated macrophages and its release into the tumor microenvironment can even be intensified by the standard chemotherapeutic agent 5-fluorouracil." (PMID 36428508, 2022). "It has been previously demonstrated that CCL20 has direct effects on neoplastic colon cancer cells causing proliferation, migration, and initiating an auto-feedback loop by inducing further secretion of CCL20." (PMID 34853656, 2021). "It has been found that colon cancer cells recruit monocytes to infiltrate tumor tissues by secreting CCL20 to bind with the monocyte receptor CCR6 in mouse model of colon cancer." (PMID 33224886, 2020). "Human colon cancers immunohistochemically stained for CCL20 showed high to moderate expression of CCL20 in the malignant epithelial cells in all 11 patient samples (data not shown), however, expression of CCL20 by infiltrating stromal cells was also noted." (PMID 24866282, 2014). "In our experimental models, we chose to evaluate the involvement of CCL20 in prostate and colon tumor growth, vascularization and invasiveness." (PMID 19340288, 2009). "To further test the role of CCL20 in the development and progression of colon cancer, we evaluated the effect of neutralizing antibodies to human CCL20 on the growth of HT-29 tumor cells." (PMID 19340288, 2009). "In addition, several studies have shown that CCL20 regulates macrophage recruitment to drive tumor growth in colon cancer and to promote breast tumorigenesis." (PMID 36045408, 2022). "We next explored whether the HGF secretion induced by CCL20 stimulation of colon cancer epithelial cells is relevant to the functional effects of CCL20." (PMID 34853656, 2021). "Interestingly, CCL20 secreting TAMs were induced via IL-6-regulated macrophage polarization in a mouse model of colon cancer; in which, CCL20 promoted cancer progression by recruiting CCR6+ lymphocytes." (PMID 34439098, 2021). "Similarly, our lab showed that the administration of PKCι inhibitor, CRT0066854, significantly reduced the expression of NF-κB target genes such as Chemokine (C-C motif) ligand 20 (CCL20) and IL-8 and decreased colon cancer cells’ growth and migration." (PMID 33375283, 2020). "Furthermore, we found that colon cancer tissues exhibited higher expressions of CCL20 and CXCL16, but similar expressions of CCL21 and CXCL10 as compared with unaffected tissue, which is in line with previous studies." (PMID 27517754, 2016). "Moreover, overexpression of CCL20 or CXCR4 in prostate and colon cancer cells promotes tumor growth that was neutralized with anti-CCL20 antibodies." (PMID 19340288, 2009). "Similar to CCL20, HGF induces migration, autofeedback CCL20 secretion, and ERK1/2 phosphorylation in the colon cancer cells." (PMID 34853656, 2021). "In this study, we show that CCL20 stimulation induces hepatocyte growth factor (HGF) production and phosphorylation of its receptor c-Met by colon cancer neoplastic epithelial cells." (PMID 34853656, 2021). "Of these, six mRNA including ECM1, GZMB, KLK10, CCL20, MMP9, and IL7 have been previously reported to have a prognostic role in colon cancer." (PMID 29377588, 2018). "Circulating MAIT cells exhibited high levels of CCR6 and CXCR6, and their corresponding chemokines, such as CCL20 and CXCL16, were strongly expressed in colon cancer tissues." (PMID 27517754, 2016). "Next, the expression of the two markers, CCL20 and CCR6, were compared in UCAC and sporadic colon cancer." (PMID 24179507, 2013).
colon carcinoma (continued). "We found that in addition to PC3 cells, CCL20 was secreted by promyelocytic leukemia (APL) cell lines, NB4 and HL60, by primary blasts of patients with acute myelocytic leukemia, human HT-29 colon carcinoma cells as well as and by normal keratinocytes." (PMID 19340288, 2009). "We therefore concluded that neutralizing antibodies to CCL20 suppressed in vivo CXCR4-dependent and independent prostate and colon tumor growth." (PMID 19340288, 2009). "CC-chemokine ligand 20 (CCL20) and its selective receptor CCR6, known to be responsible for the chemoattraction of TAMs in homeostatic conditions, have been recently found to be involved in metastatic progression of colon cancer." (PMID 36045408, 2022). "While the levels of CCL20 in both non-diseased colonic tissue and colon cancer varied substantially between patients, a significant increase of CCL20 was observed in the tumors compared to the matched controls." (PMID 24866282, 2014). "A number of genes such as CCL20, CD36 and IL18RAP individually showed significant correlations with clinical variables in colon cancer such as tumor stage (T1 to T4), lymph node status (N0 to N2), metastasis (M0 or M1), pathological grade (G1 to G4) and Duke stage (A to D)." (PMID 23536776, 2013). "Interestingly, unlike CCL20, HGF does not induce proliferation of colon cancer cells, and CCL20-dependent cell proliferation is not blocked by direct HGF inhibition." (PMID 34853656, 2021).
gastric cancer (19 papers, 2010 to 2025). A primary or metastatic malignant neoplasm involving the stomach. "We identified 12 driver genes potentially involved in the gastritis-to-cancer transformation, with CHI3L1, MMP12, CXCL6, IDO1, and CCL20 emerging as the top five genes via a early gastric cancer diagnostic model." (PMID 40108688, 2025). "While biomarkers like CXCL1 and CCL20 are linked to H. pylori–driven inflammation, their elevation in H. pylori gastric cancer samples indicates broader relevance to gastric cancer pathology." (PMID 40445003, 2025). "Low BNC1 expression correlates with advanced pathological stage and lymph node metastasis, while high CCL20 expression is associated with lymph node metastasis in gastric cancer patients." (PMID 40444282, 2025). "Moreover, CCL20 has been implicated in the progression of various cancers, such as liver, colon, breast, pancreatic, and gastric cancers." (PMID 38605947, 2024). "CCL20 is linked with the development of gastric cancer, but this gene may be liable for the progression of BRCA." (PMID 31311202, 2019). "The qPCR validation showed that PTPRC, SERPINB9, and RAC2 had low expression in gastric cancer cells, whereas only CCL20 and BANK1 were highly expressed." (PMID 40444282, 2025). "In conclusion, this study demonstrates that BNC1 inhibits the development and progression of gastric cancer cells by acting on the CCL20 promoter to mediate the JAK-STAT signaling pathway." (PMID 40444282, 2025). "Through a series of cellular biological experiments and analyses of clinical sample data, CCL20 was confirmed to be highly expressed in gastric cancer tissues." (PMID 40444282, 2025). "This study identifies BNC1 as a novel tumor suppressor and proposes CCL20 as an oncogene in gastric cancer." (PMID 40444282, 2025). "This study established that BNC1 functions as a tumor suppressor in gastric cancer cells and negatively regulates its target gene, CCL20." (PMID 40444282, 2025). "The current study further validates the oncogenic role of CCL20 in gastric cancer, underscoring its significance in the disease’s pathology and highlighting its potential as a therapeutic target." (PMID 40444282, 2025). "IHC staining analysis of gastric cancer tissue samples (n = 37) revealed that CCL20 is highly expressed in tumor tissues relative to adjacent normal tissues." (PMID 40444282, 2025). "CCL20/CCR6 induced gastric cancer EMT through the activation of the AKT pathway in response to CrkL; similar results were found with CCL21/CCR7 axis activated JAK2/STAT3 signaling pathways in promoting stemness of OSCC EMT progression." (PMID 34943853, 2021). "CrkL knockdown also resulted in a decrease in CCL20-induced migration and invasion of gastric cancer cells." (PMID 33801580, 2021). "CCL3 and CCL20-recruited DCs modified by adenovirus-trasnsduced, tumor-associated antigen, MAGE-1, can stimulate anti-tumor immunity specific to gastric cancer ex vivo and in vivo." (PMID 20420712, 2010). "Previous studies have shown that CCL20 induces migration and invasion of gastric cancer cells." (PMID 40444282, 2025). "SiRNA technology was used to effectively silence CCL20 expression in gastric cancer cell lines." (PMID 40444282, 2025). "In summary, these findings suggest that BNC1 may regulate CCL20 expression in gastric cancer cells through direct binding to the CCL20 promoter region, inhibiting its transcriptional activity." (PMID 40444282, 2025). "Additionally, wound healing and Transwell invasion assays demonstrated that CCL20 knockdown markedly suppressed the migratory and invasive capacities of gastric cancer cells compared to controls." (PMID 40444282, 2025). "PPI network analysis highlighted eight key hub genes (CD80, CCR9, CXCR3, CXCR5, CXCR6, CCR3, CCL20, and CXCL1), revealing their pivotal roles in gastric cancer and H. pylori infection." (PMID 40445003, 2025).
gastric cancer (continued). "Several identified hub genes, including CXCL1, CCL20, IL12B, STAT4, and CD80, are involved in chemokine signaling, immune modulation, and inflammation, which can promote H. pylori–mediated gastric cancer." (PMID 40445003, 2025). "Mechanistically, BNC1 suppresses CCL20 expression by binding to its promoter, leading to reduced activation of the JAK-STAT signaling pathway and promoting apoptosis in gastric cancer cells." (PMID 40444282, 2025). "Here, we found that the expression of IL-8, NF-kB p65 subunit, CCL20, ICAM1, and beta-catenin as cancer stem cell markers was significant after infection for 24 h of infection, as was observed in the 2-D gastric cancer cells." (PMID 37047540, 2023). "CrkL knockdown inhibited CCL20/CCR6-induced EMT marker expression and ERK phosphorylation in gastric cancer cells by decreasing expression of N-cadherin, vimentin, and MMP2." (PMID 33801580, 2021). "Using the top eight upregulated genes (SLPI, PLA2G2A, CXCL1, CCL20, REG1A, CLDN7, PI3, LGALS3) as a representative gene set for the high metabolic subcluster, we calculated the GSVA score of this gene set for each patient in the TCGA gastric cancer cohort." (PMID 38831933, 2024). "In addition, MK1775 treatment significantly increased the expression of proinflammatory cytokines such as CCL20, CXCL10, and IFN-β in MUS81 knockdown cells, but increased expression modestly in parental gastric cancer cells." (PMID 34625086, 2021). "Furthermore, these CCL3 and CCL20-recruited DCs, when modified with tumor antigen gene MAGE-1, could induce not only an effective CTL response against gastric cancer cells ex vivo but also therapeutic, anti-tumor immunity in both subcutaneous tumor and pulmonary metastatic tumor models." (PMID 20420712, 2010). "On the other hand, CrkL played a crucial role in mediating the EMT induced by the CCL20/CCR6 axis through the Akt signaling pathway, rather than the Erk1/2 pathway during gastric cancer development." (PMID 40362257, 2025). "IL8, CXCL9/MIG, CCL3/MIP-1α, CCL20/MIP-3α, PDGFR-B and TIMP1 plasma levels were significantly different between the non-malignant group and the gastric cancer group." (PMID 21092330, 2010). "CCL20/MIP-3α, TIMP1, IL8, PDGFR-B, CCL3/MIP-1α and CXCL9/MIG were significantly elevated in the plasma from the gastric cancer patients compared to the plasma from individuals with no visible upper gastro-intestinal pathology or those with benign lesions in stomach." (PMID 21092330, 2010). "In addition, median plasma levels of IL8, CXCL9/MIG, CCL3/MIP-1α, CCL20/MIP-3α, PDGFR-B and TIMP1 proteins were significantly different between the non-malignant group and the gastric cancer group." (PMID 21092330, 2010). "In addition, we have shown some of the proteins (CCL20/MIP-3α, TIMP1, IL8, PDGFR-B, CCL3/MIP-1α and CXCL9/MIG) to be detected at a higher level in the plasma from gastric cancer patients than in patients with non-malignant gastric conditions or with normal gastric mucosa." (PMID 21092330, 2010).